CD4 (CD4 molecule)
Diseases named in the same sentence as CD4 in open-access papers (continued):
Sharing a sentence is not in itself a finding about the gene and the disease.
tumor (continued). "Examining splenic and tumor-infiltrating lymphocytes, anti-IL-6R promoted the amounts of splenic CD4(+) helper T cells, CD8(+) CTLs and NK1.1(+) cells but not CD4(+)/CD25(+) Tregs as compared to isotype IgG treatment." (PMID 38505617, 2024). "Moreover, the tumor SUVmax of 68Ga-FAPI exhibited a strong negative correlation with both tumoral infiltrated CD8+ and CD4+ immune cells using linear regression analysis and Pearson coefficients." (PMID 38175716, 2024). "Thus, HMGB1 induces the appearance of active NK cells, as well as non-canonical CD4+ and CD8+-T lymphocytes, killing HLA-negative tumor cells that have escaped immune control." (PMID 38203798, 2024). "In ordinal logistic models adjusted for age, sex, study batch, and cancer site, MSI-high status was associated with greater odds of higher density quantile for CD3+CD4+ naive and regulatory subsets, all CD3+CD8+ subsets, double negative T cells, and CD3- non-tumor cells in epithelial tissue areas." (PMID 39763680, 2024). "Given the redundancy that exists across the chemokine network, it is quite likely that the CCR5-MIP-1α interaction may not be essential for the enhancement of CD4+ and CD8+ anti-tumour responses." (PMID 38672174, 2024). "Systemic depletion of CD8+ T cells, but not of CD4+ T cells, significantly reduced RT-induced mouse survival, arguing that the RT-induced CTL response made a major contribution to the control of the TC-1 tumor by RT." (PMID 38349740, 2024). "Through staining of CD4, CD8, HLA-DR, Ki-67, MHC-I, and synaptophysin, the level of MHC-I+ and MHC-II+ tumor cells in ONB were interrogated as a potential mechanism responsible for the lack of T cell tumor parenchyma trafficking." (PMID 38822345, 2024). "Ki67‐positive/negative tumor carries useful information regarding prognosis but the inclusion of other features from different immune cells, such as CD4 and CD8 positive cells, and interaction of immune cells with Ki67‐positive/negative tumor cells merit investigation in future work." (PMID 37873865, 2024). "Enhanced anti-tumor cytotoxic T lymphocyte (CTL) responses were induced by FKN-DC, and in these two models, therapeutic activities were completely abrogated in mice lacking either CD4 or CD8 T cells." (PMID 39125578, 2024). "Furthermore, upregulated CXCL14/17 expression showed negative correlation with the abundance of three tumor-infiltrating lymphocytes (CXCL14: Tcm CD8, Act CD4, CD56dim; CXCL17: Tcm CD8, Act CD4, Tem CD4)." (PMID 38232115, 2024). "In CESC patients, VDR expression was positively correlated with neutrophils (Cor=0.229, P=1.18e-04) and dendritic cells (Cor=0.245, P=3.86e-05) and negatively correlated with tumor cell purity, but not with the abundance of B cells, CD8+ T cells, CD4+ T cells, and macrophages." (PMID 39268267, 2024). "However, there were no significant changes in MΦs, CD206+ MΦs, general T cells, and CD4+ and CD8+ T-cell subsets in OE tumours, indicating that PGLYRP1 does not likely influence the infiltration or retention of these immune subsets." (PMID 38754953, 2024). "When examining levels of tumor-infiltrating lymphocytes (TILs) in Cd4CreNrp1+/+, Nrp1Flox/+ and Nrp1Flox/Flox mice, we noticed a significant increase in the numbers of CD8+ T cells within tumors in Cd4CreNrp1Flox/Flox mice, but not of CD4+ T cells." (PMID 38609390, 2024). "However, lack of B2m in MC38 tumor cells resulted in a significant decrease in tumor-infiltrating macrophages, DCs and CD8+ T cells, without appreciable impact in CD4+, Tregs, or NK lymphocytes." (PMID 38427670, 2024). "At all time-points, treatment with VVL-m12, but not VV CTRL or PBS resulted in significant increase in CD4+ TIL, and more predominantly CD8+ TIL, in the tumor tissue demonstrating that VVL-m12 acts primarily via adaptive CD4+ TIL and CD8+ TIL to mediate antitumor effects in this model." (PMID 39840061, 2024).
tumor (continued). "There is accumulating clinical evidence that CD4+ Treg cells, together with other immune-regulatory cell subsets, play an important role in liver cancers, such as HCC, through the inhibition of protective non-specific and tumor-specific immune responses." (PMID 39408071, 2024). "Unlike CD4+ T cells, which indirectly regulate other immune cells (such as CD8+ T cells, B cells, and macrophages) to help eliminate tumor cells, CD8+ T cells directly attack and destroy tumor cells." (PMID 39867914, 2024). "Tumour purity adjusted estimation of intra-tumoral B and T cell infiltration showed a negative correlation between PAK4 and CD8 + T cell infiltration, but not with B cells or CD4 + T cells." (PMID 38797819, 2024). "Consistently, gene expression and FACS analysis revealed that ME49Δompdc vaccination significantly increased the percentage of CD4+ and CD8+ T cells in tumors and spleens, but not in tumor‐draining lymph nodes (TDLNs), while lowering the expression of PD‐1 in these splenic and intratumoral T cells." (PMID 39031880, 2024). "Apart from CD4+ T cells not expressing CD25, Tregs were also documented for their ability to eliminate DCs, one of the most important surveillance mechanisms for the removal of cancer cells in the tumor microenvironment." (PMID 38571964, 2024). "Finally, we analyzed the relationship between TIM‐4 expression and lymphocytes in non‐tumor cells, and the results showed that there was no linear relationship between the proportion of CK‐19−TIM‐4+ cells and CD4+/CD8+/CD4+FOXP3+ cells." (PMID 39235042, 2024). "However, the polarisation of a large proportion of CD4+ TILs (40-75% FoxP3-T-bet-) cannot be confirmed, suggesting that MC38 tumours are also infiltrated by other T helper subsets not identified here." (PMID 37153625, 2023). "Furthermore, both Breg subsets from tumor-bearing mice treated with Rat IgG, but not those treated with GSK, showed stronger inhibition on IFNγ production by CD4 T cells than the Breg counterparts from naïve mice." (PMID 37291146, 2023). "Furthermore, the combination did not affect the proportion of CD4+ T cells and CD8+ T cells in CD3+ T cells in the spleen of tumor‐bearing mice." (PMID 36373232, 2023). "Further studies found that IL-37 could directly stimulate the activation and proliferation of CD4+ rather than CD8+ T cells in vitro, and prevent tumor growth in mice." (PMID 37928545, 2023). "These scRNA-seq profiles were later compared to multiple tumor types (skin melanoma, lung, colorectal, and breast cancer) and helped in analyzing the state of the immune cells in them (for example, activated CD8+ but not CD4+ T cells in the tumor setting)." (PMID 37176128, 2023). "Other factors that affect the effectiveness of treatment include the absence of tumor expression of MHC class I molecules, low numbers of CD4+ T cell infiltrates in tumor tissue, high numbers of myeloid-derived suppressor cells (MDSC), and low expression of PD-L1 on cancer cells." (PMID 37901223, 2023). "Moreover, the tumor-infiltrating CD8+ T cells, but not CD4+ T cells nor Treg cells, was significantly increased in LLC tumors derived from Usp5 cKO mice." (PMID 37208329, 2023). "However, TIGIT + CD4 + T cells and TIGIT + CD56 + NK cells rates in pre-treatment tumor were not statistically significantly correlated with TRG (p > 0.05)." (PMID 35794399, 2023). "Notably, SCC VII tumor cells do not express MHC-II and in vitro treatment with IFN-γ did not induce MHC-II expression, suggesting that CLTCH129>Q-specific CD4+ T cells are unable to directly recognize tumor cells even under inflammatory conditions in vivo." (PMID 37400675, 2023). "Furthermore, the absolute numbers of CD3+, CD4+ and CD8+ T cells in the anti-IL-6 treatment and cryo-thermal therapy groups were not significantly different from those in the tumor-bearing group." (PMID 37108179, 2023).
tumor (continued). "A derivative of the murine ovarian ID8 model has previously been targeted with neoantigen vaccines that increased the proportion of activated CD4+ and CD8+ T cells but did not result in T cell–mediated tumor control due to insufficient MHC-presented neoantigen epitopes." (PMID 38075247, 2023). "However, cell counts of CD45+, CD3+ T, CD3+CD4+ Th, CD3+CD8+ CTL, CD19+ B and CD16+CD56+ NK were not affected by tumor type (P > 0.05)." (PMID 38102684, 2023). "As a whole, the data indicated that the activation of CD4+ T, rather than CD8+ T was the potential reason why blockage of Tim-3 could significantly enhance the anti-tumor immunity of S100." (PMID 37771774, 2023). "The results of the CD4+ T population differed completely, as patients who did not achieve MPR appeared to have a lower tumor-infiltration of CD4+ T cells (p = 0.043 in NAPC patients), although differences for NAC patients were not statistically significant (p = 0.16 in NAPC)." (PMID 37771774, 2023). "Given that SCC VII tumor cells do not express MHC-II, we reasoned that CLTCH129>Q-specific CD4+ T cell-mediated protection may be dependent on their role as helper cells for CD8+ T cells." (PMID 37400675, 2023). "Co-depletion of CD4+ T cells and CD8+ T cells completely abolished the durable antitumor immune memory induced by the combination therapy, and NK-cell depletion did not affect tumor growth." (PMID 37291128, 2023). "Unlike CD4+ T cells infiltrating the tumor, CD4+ T cells in secondary lymphoid tissue had either unchanged or lower expression of these WNT components/target genes when compared with tumor-bearing mice within the control group." (PMID 36239683, 2023). "Although, CD3+ cells, CD4+ T cells, CD8+ T cells in rIL‐1α treated group were not higher compared to saline and Blank_CPH:SA MPs, there were significantly higher IFNγ+ CD8+ T cells, which explains the observed anti‐tumor response in rIL‐1α treated mice." (PMID 37206237, 2023). "CD4+ T cells did not have the same tumor cell-eliminating capacity as CD8+ T cells, confirming that the induced brain-resident CD8+ T cells, but not CD4+ T cells, provide immune surveillance of the previously encountered tumor antigen." (PMID 36759517, 2023). "The tumor modulating effect of SEA-TGT was examined in another syngeneic model, MC38, and here a more prominent, significant decrease of Tregs was observed, though no changes in CD4 or CD8 were seen in this model." (PMID 38022590, 2023). "However, CD25 is not a specific marker to CD4+Treg, and the combination of CD25-targeted therapy with tumor vaccines can suppress the generation of tumor-specific T cells, limiting the application of CD25 antibodies." (PMID 38250084, 2023). "We also explored the relationship between tumor size and the level of TILs and demonstrated that tumor size was negatively correlated with CD4+ T cells, CD4+CD127+ T cells and Treg cells infiltration in NAC, while tumor size was not correlated with lymphocyte infiltration in NAPC." (PMID 37231145, 2023). "The levels of the main methionine transporters of CD4 T cells, including SLC7A5 and CD988, which form a heterodimeric structure comprising SLC7A5 and SLC3A2, were not markedly reduced in tumor-infiltrated CD4 T cells compared to those in CD4 T cells from tumor-free mice." (PMID 37147330, 2023). "Importantly, depletion of CD8+ T cells, but not CD4+ T cells, in ABX-treated B16-F0 tumor-bearing mice dampened the antitumor effect of butyrate combined with anti-PD-1." (PMID 37635362, 2023). "This was observed without any changes to CD4+ and CD8+ T cells in the tumor." (PMID 37631236, 2023). "The study demonstrated that radiotherapy induced the redistribution of immune cells in the tumour environment, specifically manifested as: CD8+T and CD4+T cells decreased, while Tregs did not change significantly, resulting in an impaired anti-tumour immune response." (PMID 38259489, 2023).
tumor (continued). "Interestingly, anti-PD-L1 treatments did not significantly change the proportions of intratumoral CD4+ and CD8+ T cells but significantly decreased the percentages of tumor-infiltrating PD-L1+ myeloid and lymphoid cells, compared to the control group." (PMID 36969495, 2023). "Importantly, only the depletion of CD4+ cells, but not CD8+ cells prior to immunization was able to abrogate the tumor protection by NEC immunization." (PMID 38196632, 2023). "Moreover, the IL-34KO HM-1 tumor exhibited a large infiltrating of CD4+ T and CD8+ cells; these data indicate the increase in T cell infiltration in the IL-34KO HM-1 tumor is not dependent on PD-1 inhibition." (PMID 36798830, 2023). "However, the other immune cell populations, such as CD3+CD4+ helper T cells and CD3+CD8+ cytotoxic T cells, exhibited no significant changes in either tumor-dissociated or peripheral samples." (PMID 37205112, 2023). "However, high CD226 expression levels on CD4+ and CD8+ T cells did not correlate with CD3+ density in or around the tumor." (PMID 36717657, 2023). "Immunofluorescent staining of 4 NQO tumor lesions indicated that a significant increase in PD-L1 production was observed in the lesions of knockin Gln LOX-PP mice compared to wildtype Arg LOX-PP mice, and this production was not by CD4+ T cells." (PMID 37298359, 2023). "However, when compared to non-tumor bearing mice, K562 increased the expansion of NK-cell and CD3+/CD4-/CD8- T-cells in mice receiving exercise-mobilized but not resting lymphocytes, 1-2 weeks after DLI." (PMID 37077913, 2023). "Expression of CD69, a marker for tissue-resident lymphocytes, was more frequently expressed toward the tumor center on CD16− NK cells and CD8+ T cells and in a similar but non-significant trend on CD4+ T cells, while nearly all ILCs expressed CD69 at all locations studied." (PMID 37448786, 2023). "Therefore, when the tumor does not express or has a low expression of costimulatory molecules, the activation of CD8+ T cells also requires the help of activated CD4+ Th cells." (PMID 36872320, 2023). "Particularly, CD4 T cells and interferon (IFN)-γ control tumor growth without CD8 T cells." (PMID 37147330, 2023). "Flow cytometric analysis of intracellular cytokine production revealed a greatly increased accumulation of CD4+ and CD8+ IL-4+ T cells in the draining lymph nodes of LY2-injected HNSCC tumor-bearing mice compared to non-tumor-bearing mice, but not in the MOC2 HNSCC model." (PMID 37444444, 2023). "Notably, the majority of CD4+ TILs in MC38 tumours did not express FoxP3 or T-bet (40-75%), suggesting that MC38 tumours are heavily infiltrated by effector subsets other than TH1 and TREG cells, likely TH2 or TH17 cells." (PMID 37153625, 2023). "The expression levels of the checkpoint inhibitory molecule PD-1, the cell activation marker CTLA-4, the cytotoxic molecule granzyme B, and the cell proliferation marker Ki-67 by tumor infiltrating and splenic CD8+ and CD4+ T cells were not different between the groups." (PMID 35514996, 2022). "Notably, EpCAM BiTE induces CD4+ and CD8+ T-cell activation in the presence of EpCAM-positive tumor cells, like 4T1 and MC38-EpCAM, but not EpCAM-negative tumor cells, such as H22 and MC38." (PMID 36451817, 2022). "As these data were generated from bulk analyses of tumor RNA, we could not a priori attribute them to CD8+ or CD4+ T cells." (PMID 35361728, 2022). "Here, similar proportions and numbers of effector CD4+ and CD8+ T cells existed in the peritoneal fluid of vaccinated naïve and tumor-challenged mice, further supporting the lack of pseudoprogression following vaccination of tumor-bearing mice." (PMID 36142437, 2022). "Bright expression of PD-1 was demonstrated on tumor cells in most cases other than diminished or absent CD3 and CD7 and it could clearly distinguish neoplastic T cells from normal/reactive CD4-positive T cells." (PMID 36160159, 2022).
tumor (continued). "We further found that DIM treatment could not improve the percentage of CD4 + and CD8 + T cells and the concentration of IFN-γ in miR-21−/− tumor-bearing mice." (PMID 35773674, 2022). "Although the rosetting CD4+ T cells form an immunological synapse between CHL cells, and are likely activated by tumor-specific antigen, they do not expand due to immune regulatory mechanisms, such as immune checkpoint molecules and production of immunosuppressive cytokines." (PMID 35741318, 2022). "Interestingly, αCD39 reduced the total number of T cells isolated from the tumor, but the ratios of CD8+/Treg and CD4+ Treg/Teff were largely not changed, suggesting that depleting CD39+ TAECs and TAMs acts as a dominant mechanism." (PMID 35775486, 2022). "In addition, the efficacy of the combination therapy to inhibit tumor progression mainly depended on CD8+ T cells, depended partly on CD4+ T cells, and was independent of NK cells in the mouse models." (PMID 35260434, 2022). "Interestingly, we found a significant negative correlation between tumor weight and CD8+ Teffs, CD4+ Teffs, cDC2, or neutrophil frequency in mice treated with CTLA-4 blockade in combination with 7HP349." (PMID 35552271, 2022). "Using scRNAseq data from patient samples of primary and recurrent GBM (GSE154975), we identified multiple cell types based on markers from the original study: macrophages (ITGAM), T cells (CD3E), Tregs (CD4, CD3E, FOXP3), low-reads/dying cells (MALAT1), and tumor/normal brain cells (GFAP, SOX2)." (PMID 36591276, 2022). "To further confirm the potential role of IL-21 in mediating chemoimmunotherapy response, we used flow cytometry analysis and demonstrated that CD4+IL21+ cells were significantly higher in MPR tumor tissues than those in treatment-naive and non-MPR tumor tissues." (PMID 35831283, 2022). "We evaluated their ratio in tumor tissues and spleen by flow cytometry and confirmed that IBC could significantly increase the accumulation of CD8+ T cells in tumor tissue and spleen, while IBC did not affect the frequencies of CD4+ T cells and NK cells." (PMID 36091768, 2022). "Although the proportion of Tregs to total immune cells did not significantly differ according to tumor HK2 expression, the proportion of Tregs to CD4 + T-cells showed a significant positive correlation with tumor HK2 expression (spearman rho = 0.480, P = 0.003)." (PMID 36320008, 2022). "In the absence of a tumour, captopril significantly increased the proportion of CD8+ T lymphocytes (37.0% vs. 59.0%, control vs. treatment) while reducing the proportion of CD4+ and DN T lymphocytes." (PMID 35563674, 2022). "Since CD8+ and CD4+ T cells avoid hypoxic areas, through this reversal, it is possible to prevent the inhibition of antitumor immunity, generating an immunopermissive TME with an enhancement of tumor infiltration by antitumor CD8+ but not CD4+ T cells." (PMID 35681719, 2022). "Furthermore, in T cells stimulated with CD3/CD28 antibodies in the absence of tumor antigen, hypoxia remains capable of suppressing the effector expression of CD8+ and CD4+ T cells." (PMID 35840558, 2022). "Intriguingly, MΦ depletion abrogated the tumor growth control, as well as the increased frequencies of various immune cell subsets observed in BCG-treated, non-depleted mice, such as CD8+ and CD4+ T cells, NKT and NK cells, MΦ and DC." (PMID 35732347, 2022). "When all tumor samples analyzed without stratifying subtypes, CXCL14 expression showed negative correlation with infiltration of myeloid derived suppressive cell (MDSC), CD4+ Th1 and CD4+ Th2 cells." (PMID 36012586, 2022). "In addition, we did not investigate the effective CD4+ and CD8+ T cells that infiltrate the tumor site and tumor-draining lymph nodes." (PMID 35326528, 2022). "Although we observed a certain amount of CD4+ T cells in the non-RAG KO OT-I mice, we have not evaluated the proportion of conventional vs regulatory CD4+ T cells (Treg) cells and anti-tumor activity in control mice." (PMID 36330506, 2022).